MYL2 (myosin light chain 2)
Diseases named in the same sentence as MYL2 in open-access papers (continued):
Sharing a sentence is not in itself a finding about the gene and the disease.
gout (3 papers, 2016 to 2018). A condition characterized by painful swelling of the joints, which is caused by deposition of urate crystals. "Recently, a genome-wide association study identified an association between gout and a single nucleotide polymorphism (SNP) rs2188380, located on an intergenic region between MYL2 and CUX2 on chromosome 12." (PMID 27181629, 2016). "An intergenic SNP rs2188380 located between MYL2 and CUX2 gene, and rs4766566 of CUX2 gene were associated with gout in two reports of Japanese male population." (PMID 30123371, 2018).
melanoma (3 papers, 2018 to 2026). A malignant, usually aggressive tumor composed of atypical, neoplastic melanocytes. "In BRAF-mutant melanoma cells, BRN2 transcriptionally represses the expression of PDE5A (cyclic nucleotide phosphodiesterase 5A), leading to increased cGMP levels and phosphorylation of MYL2 (myosin light chain 2) and consequently increased invasion." (PMID 30866509, 2019). "In melanoma and glioblastoma cells, MerTK inhibition mediated abrogation of migration and invasion by altering signaling through total and phosphorylated FAK, RhoA, and total and phosphorylated myosin light chain 2 (MLC2)." (PMID 29554921, 2018).
schizophrenia (3 papers, 2017 to 2024). A major psychotic disorder characterized by abnormalities in the perception or expression of reality. "MYL2 is also involved in the AMPK pathway, which regulates energy balance in eukaryotes, and abnormal expression of MYL2 is associated with schizophrenia." (PMID 38338822, 2024). "A GWAS study found that the susceptibility genes of schizophrenia were associated with mRNA levels of MYL2 (p < 1.0E − 4)." (PMID 32565801, 2020). "CCDC141 (also known as CAMDI) encodes the coiled-coil domain containing 141 protein and interacts with DISC1 (disrupted in schizophrenia 1) and MYL2 (phosphorylatable myosin light chain)." (PMID 28379579, 2017).
chronic heart failure (2 papers, 2013 to 2021). "MYL2 is also involved in the occurrence and development of chronic heart failure." (PMID 33785854, 2021).
idiopathic dilated cardiomyopathy (2 papers, 2025). Decreased function of the heart associated with cardiac enlargement and congestive heart failure, of unknown cause. "The observed decrease in Myl2 and Actc1 transcript levels suggests that these treatments may contribute to cellular dysfunctions typically associated with idiopathic dilated cardiomyopathy (IDC)." (PMID 39940670, 2025).
ovarian carcinoma (2 papers, 2022 to 2023). A malignant neoplasm originating from the surface ovarian epithelium. "SIK2 overexpression in human ovarian cancer cells increases F-actin expression and MYL2 phosphorylation, which significantly promotes ovarian cancer metastasis." (PMID 36731029, 2023). "Our results also revealed that SIK2 directly phosphorylates MYLK at Ser343, suggesting that SIK2 enhances cell motility and metastasis by directly phosphorylating MYLK and activating MYLK/MYL2 signalling in ovarian cancer." (PMID 35278271, 2022). "We found that SIK2 promotes MYLK mediated MYL2 phosphorylation, cell motility and metastasis in ovarian cancer." (PMID 35278271, 2022). "Our study results showed that SIK2 regulates ovarian cancer cell motility and metastasis, and that SIK2 inhibition attenuates metastasis and reduces MYL2 phosphorylation in ovarian cancer." (PMID 35278271, 2022). "SIK2 directly phosphorylated MYLK at Ser343 and activated its downstream effector MYL2, promoting ovarian cancer cell motility and metastasis." (PMID 35278271, 2022). "Our study showed that SIK2 is highly expressed in ovarian cancer and increases cell motility and metastasis by activating the MYLK/MYL2 pathway." (PMID 35278271, 2022). "Taken together, our data showed that SIK2 accelerates ovarian cancer cell motility and metastasis by promoting MYLK/MYL2 phosphorylation and that targeting SIK2 inhibits ovarian cancer metastasis in vivo." (PMID 35278271, 2022). "We have found for the first time that SIK2 regulates ovarian cancer cell motility and metastasis by directly phosphorylating MYLK at Ser343 and activating MYL2, the downstream effector of MYLK." (PMID 35278271, 2022).
skeletal myopathies (2 papers, 2023 to 2025). "Biallelic PTVs in MYBPC3, TNNI3, MYL2 and MYL3 are associated with severe, early-onset CM phenotypes, which can include additional features such as atrial and ventricular septal defects and skeletal myopathy." (PMID 38666070, 2023). "However, skeletal myopathies have only been associated with MYL1 and MYL2 genes." (PMID 40488356, 2025).
ADNP syndrome (1 paper, 2020). "In this respect, MYL2 is linked to cardiac development and function, while MYL9 is involved in smooth muscle and non-muscle cell contractile activity e.g., in the gut and urinary tract, with ADNP syndrome children suffering cardiac as well as gastrointestinal problems." (PMID 32937737, 2020).
alcohol dependence (1 paper, 2014). Physical and psychological dependence on alcohol. "Considering the involvement of dopamine and serotonin in SZ and the comorbidity of SZ with alcohol dependence and cardiovascular diseases, it is plausible that these two genes (ALDH2 and MYL2) may be related to SZ." (PMID 24454952, 2014).
colitis (1 paper, 2017). Inflammation of the colon. "CerS2 null mice exhibited severe colitis upon DSS treatment, along with increased intestinal permeability, higher myosin light chain 2 (MLC2) phosphorylation and diminished levels of junctional adhesion molecule‐A (JAM‐A) in the colon." (PMID 28699686, 2017).
colorectal cancer (1 paper, 2021). A primary or metastatic malignant neoplasm that affects the colon or rectum. "Colorectal cancer cells secrete 12(S)-HETE, which promotes CAF retraction from colorectal cancer spheroids by activating myosin light chain 2 (MLC2) through Ca2+/RHO/ROCK signaling axis, facilitating colorectal cancer cell migration into the stroma and surrounding regions." (PMID 34768796, 2021).
fibrosis (1 paper, 2024). the formation of excess fibrous connective tissue in an organ or tissue in a reparative or reactive process. "The activation of RAR/RXR by ATRA inhibited hepatic fibrosis by downregulating myosin light chain 2 (MLC-2) expression." (PMID 39478961, 2024).
gastric cancer (1 paper, 2010). A primary or metastatic malignant neoplasm involving the stomach. "Transforming growth factor-β1 (10 ng ml−1) decreased ZO-2 and E-cadherin expression in scirrhous gastric cancer cells and increased myosin light chain-2 phosphorylation (p-myosin), but not in non-scirrhous gastric cancer cells." (PMID 20145621, 2010).
head and neck squamous cell carcinoma (1 paper, 2024). A squamous cell carcinoma that arises from any of the following anatomic sites: lip and oral cavity, nasal cavity, paranasal sinuses, pharynx, larynx, and salivary glands. "MYL1, MYL2, and MYL3 were shown to have a positive correlation between expression levels and the infiltration of CD4+T cells in head and neck squamous cell carcinoma (HNSCC)." (PMID 39768172, 2024).
intrahepatic cholestasis (1 paper, 2021). A cholestasis characterized by impairment of the bile flow caused by obstruction located in the liver. "ENT, which causes drug-induced intrahepatic cholestasis, decreases myosin light chain 2 phosphorylation through myosin light chain kinase and results in BC dilation." (PMID 34151938, 2021).
left ventricular hypertrophy (1 paper, 2021). Enlargement of the LEFT VENTRICLE of the heart. "Attenuation of MYL2 phosphorylation is associated with the development of left ventricular hypertrophy resulting from depressed fractional shortening." (PMID 33498641, 2021).
metabolic syndrome (1 paper, 2018). A cluster of metabolic risk factors for CARDIOVASCULAR DISEASES and TYPE 2 DIABETES MELLITUS. "The intergenic variant rs12229654 between MYL2 and CUX2 showed a pleiotropic effect associated with metabolic syndrome, HDL, and glycemic traits." (PMID 30382898, 2018).
pancreatic cancer (1 paper, 2023). "Here, we demonstrate that retinoic acid receptor β (RAR-β) transcriptionally represses myosin light chain 2 (MLC-2) expression in pancreatic cancer cells." (PMID 37130839, 2023).
Parkinson disease (1 paper, 2023). A progressive degenerative disorder of the central nervous system characterized by loss of dopamine producing neurons in the substantia nigra and the presence of Lewy bodies in the substantia nigra and locus coeruleus. "TNF (Tumor Necrosis Factor)-α elevated inflammatory factor expression induced hippocampal neuron downregulation while accelerating the degradation of myosin light chain 2-activated caspase-3 activation and apoptosis in Alzheimer’s and Parkinson’s disease." (PMID 37691828, 2023). "The degradation of myosin light chain 2 activated cellular apoptosis in Alzheimer’s and Parkinson’s disease." (PMID 37691828, 2023).
renal carcinoma (1 paper, 2022). A carcinoma arising from the epithelium of the renal parenchyma or the renal pelvis. "In contrast, high expression of FRZB, MYBL2, MYL2, NETO2, PLSCR4, and TES predicts an unfavorable outcome in endometrial, head and neck, liver, pancreatic, and renal cancer." (PMID 36497479, 2022).
rotator cuff tears (1 paper, 2023). "In humans, increased expression of MYL1 has been identified in traumatic rotator cuff tears in female patients, whereas MYL2 is highly expressed in degenerative tears in male patients." (PMID 37645058, 2023).
tongue tumor (1 paper, 2018). "Among 24 candidates, 8 proteins including Myosin light chain family members (MYLPF, MYL4 and MYL2), creatinine kinase, serotransferrin, heat shock protein A8, carbonic anhydrase 1 and Glyceraldehyde-3-phosphate dehydrogenase were significantly downregulated in tongue tumor tissues." (PMID 29371635, 2018). "The present study identified cofilins (CFL1 and CFL2) and tropomyosin family proteins (TPM3 and TPM4) are significantly upregulated, in contrast, myosin family proteins (MYL2, MYL4 and MYLPF) were downregulated in tongue tumor samples as compared to normal samples." (PMID 29371635, 2018).
cancer (14 papers, 2010 to 2026). A tumor composed of atypical neoplastic, often pleomorphic cells that invade other tissues. "The pro-inflammatory cytokine LIF governs fibroblast activation in cancer by regulating the myosin light chain 2 activity." (PMID 27901489, 2017). "Future studies should investigate why knockdown of α-actinin-4 affects the expression of myosin II and myosin light chain 2 in cancer cell and fibroblasts." (PMID 21085685, 2010). "Among the various effectors, mDia and ROCK are two best-described effectors that are important for RhoA-mediated regulation of cancer cell invasion/metastasis by stabilizing adherens junctions, regulating myosin light chain 2 (MLC2) phosphorylation and focal adhesion dynamics." (PMID 31705019, 2019). "This MALL-SDC4 program promotes RhoA/phosphorylated myosin light chain 2 (p-MLC2)-dependent amoeboid motility and sensitizes cancer cells to Schwann cell-derived pleiotrophin, strengthening directed neural invasion." (PMID 42017444, 2026). "The study also highlights the roles of specific proteins (MYH2, MYL1, MYL2, MYH7) and microRNAs (such as hsa-let-7d-5p) that are the potential biomarkers in cancer progression founded on several analyses." (PMID 39656775, 2024). "Cancer cells co‐cultured with adipocytes also showed increased SIK2 phosphorylation at S358, and increased expression of SIK2, MYL2‐pS19 and MYLK‐pS343." (PMID 35278271, 2022). "Mechanistically, SIK2 regulated cancer cell motility and migration by myosin light chain kinase, smooth muscle (MYLK)‐meditated phosphorylation of myosin light chain 2 (MYL2)." (PMID 35278271, 2022). "For this reason, we decided to study the effect of GPER activation on myosin light chain-2 (MLC-2) phosphorylation, traction force generation and cells stiffness—mechanical properties closely related to cancer cell malignancy." (PMID 31991740, 2020). "SIK2 protein expression was positively correlated with the expression of MYL2‐pS19 (r = 0.87; Pearson correlation coefficient, P = 0.01) and MYLK‐pS343 (r = 0.83, Pearson correlation coefficient, P = 0.02) in these cancer cell lines." (PMID 35278271, 2022).
tumor (12 papers, 2017 to 2025). "HK2 was found to drive glycolysis in tumor-derived pericytes and regulate the blood vessel supporting ability of pericytes by inducing Rho-associated coiled-coil containing protein kinase 2 -myosin light chain 2 (ROCK2-MLC-2) driven contractility." (PMID 36984785, 2023). "It was previously shown that GRF2 suppresses the CDC42-dependent phosphorylation and activation of MLC2 (Myosin Light Chain 2) in cultured cell lines from different human tumor types." (PMID 37947653, 2023). "p-MLC2 (Myosin light chain-2) regulates actomyosin contractility and cell polarity, which are important for tumor metastasis by influencing immunomodulatory secretome and stiffness of metastatic niches." (PMID 37689735, 2023). "Next, the expression levels of SIK2, MYLK, MYLK‐pS343, MYL2 and MYL2‐pS19 in tumour lysates were assessed by western blot and immunohistochemistry." (PMID 35278271, 2022). "Integrin αvβ1 on CAFs participates in the fibrillar fibronectin assembly of CAFs via PDGFRα, and in myosin light chain 2 (MLC2) contractility and traction forces, which then induces directional mobility of tumor cells." (PMID 40352270, 2025). "Myosin genes MYL1, MYL2, MYH2, and MYH7 were proved significantly down-regulated but as unfavorable prognostic markers and related with tumor stages or grades in HNSCC." (PMID 37679666, 2023). "The results of the analysis showed that there was a significant decrease in the levels of MYLK‐pS343 and MYL2‐pS19 in tumour lysates from OVCAR8‐shSIK2 cells compared to OVCAR8‐shNC cells, suggesting that SIK2 regulates MYLK/MYL2 phosphorylation." (PMID 35278271, 2022). "What's more, it has been found that PKM2 with high expression in embryonic development and tumor progression is phosphorylated at T45 by Aurora B, which leads to PKM2 localization and its interaction with myosin light chain 2 (MLC2) in the contractile ring region of mitotic cells during cytokinesis." (PMID 29299177, 2017).
heart disease (6 papers, 2014 to 2022). "For four of these loci, the top gene according to OPEN had been shown to be mutated in DCM (PLN, ACTN2, TNNT2, TTN), while for two others, the top gene was known to be mutated in HCM (MYL2) or an arrhythmogenic form of cardiac disease (CASQ2)." (PMID 25633252, 2014). "While a few enhancers previously knocked-out in mice have the potential to result in cardiac phenotypes (for example, refs 43, 44), to our knowledge, the Myl2 and Myh7 enhancers are the first examples whose loss has been shown to result in a phenotype consistent with heart disease." (PMID 27703156, 2016).
myopathy (5 papers, 2008 to 2025). A disease of the muscle in which the muscle fibers do not function properly. "Whether such a response exists in dominant MYL2-missense variant associated myopathies remains to be investigated." (PMID 32453731, 2020). "Since the RLC gene (MYL2), like MYH7, is expressed in slow skeletal muscle, skeletal muscle biopsies from patients with the Glu22Lys MYL2 mutation exhibited abnormal skeletal muscle histology, similar to patients with ragged red fiber (RRF) myopathy." (PMID 19325803, 2008).
cardiovascular diseases (3 papers, 2013 to 2018). "Because MYL2 encodes the regulatory myosin light chain that associates with cardiac myosin beta heavy chain, MYL2 rs3782889 associated with risk of cardiovascular disease in a Korean population." (PMID 29632305, 2018). "For example, the ADIPOQ, AMY1A, CFB, HP and HBB are associated with the metabolic diseases, while the FBP4, HP, LPL and MYL2 are related to the cardiovascular diseases." (PMID 24204599, 2013).
metabolic disease (2 papers, 2013 to 2017). A congenital disorder (due to inherited enzyme abnormality) or acquired (due to failure of a metabolically important organ) disorder resulting from an abnormal metabolic process. "Most of these P/LP variants were found in validated minor sarcomere genes (ACTC1, MYL2 and MYL3) and genes related to metabolic diseases (GLA and PRKAG2)." (PMID 28771489, 2017).
infection (1 paper, 2019). The state of being infected such as from the introduction of a foreign agent such as serum, vaccine, antigenic substance or organism. "We selected CD83, FAM63B, MYL2 and TRAM2 knockdowns for further analysis since the silencing of these four host genes resulted in increased host cell viability regardless of the strain that was employed, and these genes were not studied before in relation to S. aureus cell infection." (PMID 31659191, 2019).
MYL2 also shares sentences with these, for which no sentence is quoted: Hypertension (3 papers); Arrhythmia (2); arrhythmogenic right ventricular cardiomyopathy (2); familial hypertrophic cardiomyopathy (2); hypertrophy (2); muscular dystrophy (2); myocardial infarction (2); Abdominal obesity (1); asymmetrical septal hypertrophy (1); centronuclear myopathy (1); Danon disease (1); familial atrial fibrillation (1); head and neck cancer (1); leprosy (1); Myocardial fibrosis (1); myocarditis (1); neurodevelopmental disorder (1); neuropathy (1); osteosarcoma (1); prediabetes (1); pulmonary hypertension (1); rhabdomyosarcoma (1); Tremor (1); Wilms tumor (1); Wolff-Parkinson-White syndrome (1).